PXN (paxillin)
Diseases named in the same sentence as PXN in open-access papers (continued):
Sharing a sentence is not in itself a finding about the gene and the disease.
colorectal cancer (continued). "It has been reported that PXN overexpression promoted colorectal cancer progression and metastasis." (PMID 36923874, 2023). "High expression of PXN was correlated with worse prognosis in liver and colorectal cancer 41-43." (PMID 33162799, 2020). "Moreover, miR-145 suppresses cell migration and invasion by targeting paxillin in human colorectal cancer cells." (PMID 29416759, 2018). "Furthermore, their levels are inversely correlated with PXN expression in gastric cancer cell lines, colorectal cancer, as well as in non-small cell lung cancer." (PMID 28214467, 2017). "We also tested tumors with signet ring morphology, as this subtype of colorectal carcinoma - although rare - is associated with worse outcomes; pY88 paxillin staining did not correlate with this subtype." (PMID 27447856, 2017). "We examined the possibility that PXN expression could be associated with Bcl-2, pBcl-2-S87, and MMP2 expression in tumors from 190 colorectal cancer patients." (PMID 25826088, 2015). "In the present study, we provided evidence from cells, xenograft tumors, and human tumors to demonstrate that ERK activation by PXN promoted tumor aggressiveness and led to poor patient outcome in colorectal cancer and that this promotion occurs via increased pBcl-2-S87-mediated MMP2 expression." (PMID 25826088, 2015). "We next examined whether PXN, Bcl-2, pBcl-2-S87, and MMP2 expression could be associated with the outcomes of patients with colorectal cancer." (PMID 25826088, 2015). "Moreover, PXN promotes tumor progression and poor outcome in colorectal cancer patients via decreased miR-137 expression." (PMID 25826088, 2015). "Thus, epithelial-mesenchymal transition might be another reason for the different prognostic implications of PXN in colorectal cancer, RCC, and BRCA." (PMID 34135128, 2021). "Moreover, colorectal cancer cells that express high levels of pY88 paxillin are sensitive to dasatinib treatment, suggesting that pY88 paxillin may serve as a predictive biomarker for Src family kinase inhibitors." (PMID 27447856, 2017). "Therefore, our data suggest that pY88 paxillin may be exploited as a predictive marker for response of colorectal cancer patients to dasatinib." (PMID 27447856, 2017). "Cox regression analysis of PXN, Bcl-2, pBcl-2-S87 and MMP2 expressions in patients with colorectal cancer." (PMID 25826088, 2015). "In the present study, we provided the evidence that the stabilization of Bcl-2 by its phosphorylation at Serine 87 via PXN-mediated ERK activation promoted tumor invasion and poor patient outcome in colorectal cancer." (PMID 25826088, 2015). "Moreover, the downregulation of paxillin also reduces the activation of extracellular regulated protein kinase (ERK) and inhibits the EMT process, thereby inhibiting colorectal cancer metastasis." (PMID 37175948, 2023). "We reported that stabilization of Bcl-2 protein via phosphorylation of Bcl-2 at Serine 87 (pBcl-2-S87) by PXN-mediated ERK activation conferred 5-fluorouracil (5-FU) resistance and an unfavorable response to 5-FU-based chemotherapy in colorectal cancer patients." (PMID 25826088, 2015).
hepatocellular carcinoma (17 papers, 2008 to 2025). A malignant tumor that arises from hepatocytes. "The lncRNA FIRRE expression was elevated in hepatocellular carcinoma and associated with MBNL3 for promoting the splicing activity of PXN or PFKFB4 for glycolysis." (PMID 38556083, 2024). "The phosphorylation of paxillin at serine 178 by JNK to form pS178-paxillin is also considered to be a potential reliable prognostic marker for hepatocellular carcinoma." (PMID 37175948, 2023). "Oncoprotein protein kinase C (PKC) plays an important role in c-Met endosomal process, while targeted disruption of PKCε blocks the c-Met-JNK-paxillin signaling pathway in hepatocellular carcinoma cell (HCC)." (PMID 32626713, 2020). "In hepatocellular carcinoma (HCC), vascular channels were formed, and these vessels were associated with RhoC FAK/Paxillin signaling regulation as well as with high expression of RhoC/ROCK2, VE-cadherin, and MMP2 mediated by ERK/MMPs signaling." (PMID 31993365, 2019). "Similarly, paxillin up-regulation correlates with the presence of extrahepatic metastasis in hepatocellular carcinoma and lymph node metastasis in breast tumors." (PMID 18492274, 2008). "One of the signaling components involved in hepatocellular carcinoma (HCC) progression is the focal adhesion adaptor paxillin." (PMID 26416447, 2015). "In hepatocellular carcinoma, ITGB1 regulated the cell cycle process via the PXN/YWHAZ/AKT pathway, promoting hepatocellular carcinoma progression." (PMID 38183097, 2024). "Paxillin is overexpressed in many carcinomas, including bladder cancer, ESCC, hepatocellular carcinoma (HCC), NSCLC, salivary adenoid cystic carcinoma, and floor of mouth carcinoma." (PMID 23209815, 2012). "We previously discovered that FAK, paxillin, and their phosphorylation levels closely correlate with HAb18G/CD147 expression in human hepatoma cells." (PMID 19775453, 2009). "The expression of paxillin in human cholangiocarcinoma, esophageal cancer, hepatocellular carcinoma, and other tumors is significantly higher than in paired normal tissues, but the expression in several tumors, such as renal papillary cell carcinoma and endometrial carcinoma, is opposite." (PMID 37175948, 2023). "Studies have shown that CD147 co-localizes with integrin α3β1 and α6β1 in hepatocellular carcinoma cells and mediates FAK-paxillin as well as FAK-PI3K-Ca2+ signaling pathways through their interaction to promote both invasive and metastatic potential of HCC cells." (PMID 37090718, 2023).
pancreatic cancer (15 papers, 2011 to 2026). "This pro-adhesive effect on pancreatic cancer cells is associated with an increase in the phosphorylation state of Akt and to a lesser extent of paxillin." (PMID 21747918, 2011). "Mechanistically, we identify the FAK–paxillin axis as a durotaxis-specific sensor and provide in vivo proof of concept that targeting this pathway prevents lung fibrosis and pancreatic cancer metastasis." (PMID 40925952, 2025). "Next, we tested the effects of paxillin inhibition with 6-B345TTQ on pancreatic cancer progression in vivo." (PMID 37607005, 2023). "Lysophosphatidic acid modulates the tyrosine phosphorylation of FAK and paxillin and their relocation and induces the rearrangement of the actin cytoskeleton and focal adhesion structures to inhibit the migration of pancreatic cancer cells." (PMID 37175948, 2023). "Wnt5a can promote the migration of pancreatic cancer cells by promoting paxillin phosphorylation through Wnt5a/JNK signaling." (PMID 37175948, 2023). "Studies have shown that pS178-paxillin can promote the reorganization of FA to promote the migration of pancreatic tumor cells." (PMID 37175948, 2023). "In our studies, deletion of integrin β1 from pancreatic cancer cells reduced the focal adhesion as determined by the phosphorylation status of paxillin, and downregulated kindlin-2 expression in pancreatic cancer cells." (PMID 34638957, 2021). "Gastrin has been shown to promote the reorientation of the Golgi apparatus and directional migration of pancreatic cancer cells by inducing the activation of paxillin." (PMID 34638432, 2021). "Flow cytometry analysis demonstrated that PXN knockdown significantly promoted the apoptosis rate in the pancreatic cancer cells anoikis." (PMID 33033511, 2020). "Suspension culture and flow cytometry assays elucidated that miR-137 inhibited clone growth and promoted the apoptosis rate in the pancreatic cancer cells anoikis, while the PXN overexpression reversed the phenotype." (PMID 33033511, 2020). "The present study showed that TNC induced migration and invasion in pancreatic cancer cells and regulated a number of metastasis-associated proteins, including the EMT markers, MMP9 and Paxillin." (PMID 29088796, 2017). "TNC can activate JNK to promote the association of Paxillin with FAK, which facilitates the motility and adhesion of pancreatic cancer cells." (PMID 29088796, 2017). "It was reported that CD44 is associated with FAK, paxillin, and Src activity, and the loss of CD24 expression significantly decreases cell proliferation, cell invasion, and metastasis nodules of CRC and pancreatic cancer in mice model." (PMID 23970932, 2013). "We next interrogated whether paxillin phosphorylation is relevantly increased in human pancreatic cancer cells that are physically adjacent to nerves in the pancreas." (PMID 37607005, 2023). "Thus, CHIP can negatively regulate PI3K/AKT/mTOR and Src/FAK/paxillin pathway activation in pancreatic cancer cells." (PMID 24722501, 2014). "Interestingly, on a FN coated surface TNC decreases pancreatic cancer cell adhesion and phospho-paxillin and phospho-Akt levels." (PMID 21747918, 2011). "Furthermore, we investigated whether PXN is the function target of miR-137 mediated pancreatic cancer cell anoikis resistance, the rescue experiments were carried out with miR-137 mimics and PXN overexpression plasmid." (PMID 33033511, 2020). "MicroRNA-137 (miR-137) is down-regulated in pancreatic cancer and promotes anoikis by modulating the AKT signaling pathway, with paxillin (PXN) identified as a target of miR-137 that promotes AKT activation." (PMID 41596231, 2026). "It was shown that TNC markedly increased the expression of p-PaxillinS178 Paxillin-dependent manner, which indicated that TNC modulates the phosphorylation of PaxillinS178 in pancreatic cancer cells." (PMID 29088796, 2017).
pancreatic cancer (continued). "It has been previously shown that Wnt5A, JNK and paxillin are overexpressed in pancreatic cancer and Wnt5A/JNK signaling stimulates cell migration in pancreatic cancer by activating paxillin." (PMID 26980710, 2016). "The upstream kinase of Paxillin, FAK, is also shown to be highly expressed and activated in many types of cancers, and has been used as a therapeutic target for cancer treatment, including pancreatic cancer and non-small-cell lung carcinoma." (PMID 36723624, 2023). "A cancer vaccine that induces neutralizing antibodies to gastrin was shown to improve survival in a murine model of pancreatic cancer and reduce metastases by decreasing components of the metastases cascade and EMT, including protein expression of paxillin, β-catenin, and MMP-7." (PMID 36614194, 2023). "We next tested whether CCL2 directly induces phosphorylation of paxillin and treated SU.86.86 and T3M4 pancreatic cancer cells with 100 ng/mL of rCCL2 for 5, 15, and 25 minutes." (PMID 37607005, 2023). "In pancreatic cancer we did not observe an altered phosphorylation of FAK and Paxillin as well as AKT." (PMID 28086938, 2017).
glioblastoma (14 papers, 2011 to 2024). The most malignant astrocytic tumor (WHO grade IV). "Recently, a pro-migratory effect of LCK was observed in glioblastoma, which has been linked to an increased phosphorylation of Paxillin on tyrosine 118, an important post-translational modification associated with migration and focal adhesion turnover." (PMID 34116687, 2021). "In our previous study, the levels of adhesion-associated proteins, including p-FAK, p-paxillin, integrin β1, and integrin β3, were reduced after knockdown of PSMB4 expression in LN229 human glioblastoma cells." (PMID 38791597, 2024). "IL-34 binds to the extracellular domain of PTPRZ1 to stimulate the phosphorylation of paxillin and focal adhesion kinase, which influences the growth and migration of glioblastoma cells." (PMID 31727934, 2019). "The effect of disrupting netrin function on adhesive complex formation in glioblastoma cells was investigated by examining the distribution of paxillin, which is present in both FAs and FCs, and zyxin, which is present in FAs but not FCs." (PMID 21980448, 2011). "Additionally, Nilotinib has been reported to stimulate other kinases, such as p130Cas, FAK, and Paxillin in glioblastoma cells independently of its known targets Abl and PDGFR." (PMID 29463296, 2018). "Bioinformatic analysis revealed that PXN and PTPN12 mRNA expression was higher in astrocytomas (Grades II, III, and IV) compared to normal brain and showed the highest expression in the mesenchymal subtype (the most aggressive glioblastoma subtype, associated with bad prognostic)." (PMID 33841333, 2021). "PXN and PTPN12 expression data from 196 grade II, 223 grade III, and 139 grade IV (glioblastoma) astrocytomas were obtained from TCGA and compared to 249 healthy human brain cortex samples from the GTEx database." (PMID 33841333, 2021). "The PXN and PTPN12 mRNA expression increased in glioblastomas compared to normal brain, and in the case of PTPN12, the expression was higher in glioblastomas compared to astrocytomas grades II and III." (PMID 33841333, 2021). "The analysis of expression among the four subtypes of glioblastomas showed that PXN and PTPN12 have the highest levels of expression in the mesenchymal subtype (the most aggressive glioblastoma subtype)." (PMID 33841333, 2021). "Taken together, these results showed that TP3 decreased mobility and migration in the glioblastoma cells via the MAPKs, AKT, and FAK/paxillin signaling pathways." (PMID 32266797, 2020). "Some of their structural and regulator components, including non-receptor cytoplasmic tyrosine kinase cSrc, Focal adhesion kinase (Fak), Paxillin (Pax), Tyrosine-protein phosphatase non-receptor type 12 (PTP-PEST), and integrins have been associated with the spread of glioblastoma cells." (PMID 33841333, 2021).
osteosarcoma (13 papers, 2008 to 2024). A usually aggressive malignant bone-forming mesenchymal neoplasm, predominantly affecting adolescents and young adults. "It has previously been shown that knockdown of paxillin in highly metastatic osteosarcoma sub-lines M112 and 132 inhibits migration, which is in direct contrast to our observation that loss of paxillin in Saos-2 cells correlates with increased motility." (PMID 23352643, 2013). "To illustrate the technique, we will analyze a migrating osteosarcoma cell expressing paxillin, a structural adaptor protein that interacts with integrins and focal adhesion kinase in focal adhesions." (PMID 29049414, 2017). "Paxillin is also overexpressed in highly metastatic human osteosarcoma and renal carcinoma cell lines." (PMID 18492274, 2008). "For example, paxillin is overexpressed and hyperphosphorylated in sublines of the osteosarcoma cell line HuO9 that are highly metastatic, compared with the low-metastatic sublines." (PMID 18492274, 2008). "Interestingly, enhanced phosphorylation of FAK, paxillin, and p130 were also detected in osteosarcoma cells, but, here, a concomitant suppression of adhesion was observed." (PMID 37373053, 2023). "Using an antibody that recognizes both the β1- and β2-adaptin components of the AP-1 and AP-2 complexes, we found that endogenous β-adaptin, which binds directly to clathrin, localizes to paxillin positive focal adhesion structures during U2OS osteosarcoma cell spreading on a collagen matrix." (PMID 23056266, 2012). "U2OS human osteosarcoma cells were transfected with GFP-actin and mApple-Paxillin and plated on fibronectin-coated traction force substrates compatible with high resolution imaging." (PMID 23923013, 2013).
non-small cell lung carcinoma (12 papers, 2013 to 2023). A group of at least three distinct histological types of lung cancer, including non-small cell squamous cell carcinoma, adenocarcinoma, and large cell carcinoma. "In non-small cell lung cancer cells, PXN activated ERK and increased the binding of CREB to the Bcl-2 promoter, elevating the Bcl-2 expression level and reducing cellular apoptosis." (PMID 36923874, 2023). "Cell division protein regulator 1 enhances the proliferation of non-small cell lung cancer by regulating the FAK/paxillin signaling pathway to promote cell cycle progression." (PMID 37175948, 2023). "ETS variant 4, a member of the ETS transcription factor PEA3 subfamily, was found to directly regulate the expression of the paxillin gene to induce the proliferation and migration of non-small cell lung cancer cells." (PMID 37175948, 2023). "Live randomly migrating H1299 (human non-small cell lung carcinoma) cells stably expressing EGFP-Paxillin (CMAC marker) and RubyRed-LifeAct (F-actin marker) (H1299-P/L cells) were imaged by confocal microscopy." (PMID 24587399, 2014). "The natural compound deguelin, as a potential antimetastatic drug in non-small cell lung cancer, exerts its antimetastatic effect by inhibiting FAK/Src/paxillin signaling by inhibiting the expression of cathepsin Z and its interaction with integrin β3." (PMID 37175948, 2023). "A recent study demonstrated that the antimigratory and anti-invasive effects of deguelin on non-small cell lung cancer are mediated by suppression of the activity of cathepsin Z and its downstream FAK/Src/paxillin pathway along with reduced phosphorylation of FAK, paxillin, and Src." (PMID 36362132, 2022).
cervical cancer (10 papers, 2016 to 2024). A primary or metastatic malignant neoplasm involving the cervix. "The new study also shows that the interaction of cold-associated tyrosine phosphorylated protein 1 with paxillin is required for the anchorage-independent growth of cervical cancer HeLa cells." (PMID 37175948, 2023). "Liu proved that PXN was significantly upregulated in cervical cancer, which associated with tumor stage, poor differentiation, and led to resistance to radiation." (PMID 35912169, 2022). "Our results provide strong evidence that genistein inhibits both the activation of the FAK/paxillin pathway and FAK and paxillin gene expression in cervical cancer cells." (PMID 36838908, 2023). "Paxillin (PXN) has been found to be markedly abundant in cervical cancer tissues and is positively correlated with tumor stage and lymphatic metastasis." (PMID 33685449, 2021). "Additionally, genistein has demonstrated anti-metastatic effects in cervical cancer cells by regulating the FAK-paxillin and MAPK signaling pathways." (PMID 39273231, 2024). "Thus, our results provide evidence that genistein suppresses cervical cancer cell metastasis by regulating the FAK/paxillin pathway." (PMID 36838908, 2023). "PXN is known to promote tumour progression in cervical cancer." (PMID 34885088, 2021). "Genistein inhibits the FAK/paxillin pathway and strongly regulates Twist/Snail-mediated EMT, two pathways related to the progression of cervical cancer." (PMID 36838908, 2023). "Lut combined with AsA treatment downregulated PI3K/AKT signaling (PI3K, AKT and p70S6K), JNK/p38 MAPK signaling and FAK signaling (integrin β1, paxillin and FAK) and upregulated ERK signaling to induce apoptosis and inhibit cancer cell migration, resulting in an anticancer effect on cervical cancer." (PMID 36672499, 2023).